CRP (C-reactive protein)
Diseases named in the same sentence as CRP in open-access papers (continued):
Sharing a sentence is not in itself a finding about the gene and the disease.
bacterial infection (continued). "The patient was suspicious for a bacterial infection and had fever, nausea, was vomiting, and had a CRP of 27 mg/L." (PMID 33319340, 2021). "Similar to our study, numerous studies have confirmed that PCT levels have a higher specificity than CRP levels for bacterial infections." (PMID 34344141, 2021). "At a cut-off of 172 mg/L (AUC of 86% (95% CI 78–93%), CRP had a sensitivity of 81% and a specificity of 76% for the detection of secondary bacterial infection." (PMID 34021897, 2021). "Next, the accuracy of the IMS to detect all bacterial infections combined compared to CRP and PCT was calculated." (PMID 33647009, 2021). "Several studies and meta-analyses have shown that procalcitonin (PCT) and other inflammatory blood markers [C-reactive protein (CRP) and white blood cells (WBC)] are reliable diagnostic markers of bacterial infection in the adult population." (PMID 34344141, 2021). "Consistent with our data, several studies have identified PCT as a more reliable biomarker compared to CRP for the prediction of bacterial infection, both at FN presentation as well as in serial measurements." (PMID 34093531, 2021). "Next, the levels and diagnostic positive rate of PCT, CRP and WBC between G+ and G− bacterial infection group were depth comparative analyzed." (PMID 34836530, 2021). "Most recently, bacterial infection is suspected when s-CRP is greater than 100 mg/L in the clinical context." (PMID 34675320, 2021). "Our findings suggest that the UTIs seem to be highly unlikely in patients with bacterial infections and with a specific inflammatory pattern consisting of severely raised CRP values and platelet indices within the normal range." (PMID 34573189, 2021). "The primary objective was to assess the best CRP cut-off to distinguish a viral from a bacterial infection; the secondary objective was to evaluate other biomarkers for the same purpose." (PMID 34574070, 2021). "Zarkesh et al11 considered that IL‐6, CRP, WBC, and absolute neutrophil counts have diagnostic value to predict serious bacterial infection." (PMID 34725873, 2021). "There is debate as to what CRP concentration should be used to determine if a bacterial infection is likely and an antibiotic required." (PMID 34748558, 2021). "Hasan and his colleagues added that the advantages of PCT over CRP are that its level increases mainly in bacterial infection, and its normal level is rapidly restored after antibiotic therapy." (PMID 33061986, 2020). "Patients with high CRP and positive viral PCR represent patients with secondary bacterial infection." (PMID 33138859, 2020). "In our study, the decision limit for CRP was chosen in accordance with other human studies which often use cut-off values of 100 mg/l to rule in a bacterial infection and apply antibiotics." (PMID 32434519, 2020). "For the OFI group, while the same trend was seen in patients clinically diagnosed with bacterial infection, CRP level among patients with viral diagnosis was lower for those enrolled at a later time point." (PMID 32063229, 2020). "In humans, CRP mediates several mechanisms of host defense from bacterial infection through complement activation, regulation of phagocytosis, and the binding of various antigens on the cell membranes." (PMID 33096884, 2020). "ROC analysis indicated that PCT level was the best predictor for bacterial infections in NNLCPs, demonstrating the highest AUC, followed by CRP level and NLR." (PMID 32908505, 2020). "During bacterial infections CRP can bind to polysaccharides such as polycholine on microorganisms which triggers the classical innate complement pathway with activation of C1q." (PMID 32932765, 2020). "Some studies have used CRP together with other parameters to predict children with severe bacterial infection." (PMID 32429293, 2020).
bacterial infection (continued). "Despite decades of research for a “gold standard” biomarker of invasive bacterial infections, only few biomarkers have been translated into routine clinical practice, with C-reactive protein (CRP) and procalcitonin being the most frequently used." (PMID 33214628, 2020). "High values of CRP are prevalent in patients with primary herpetic gingivostomatitis, similar to adenoviral infections and some bacterial infections." (PMID 33081701, 2020). "The sensitivity and the specificity of elevated serum CRP level in predicting the two most common bacterial infections; either S. pneumoniae or H. influenzae were 0.71 (95% CI 0.47–0.87) and 0.72 (95% CI 0.58–0.83), respectively." (PMID 30685351, 2020). "Laboratory tests revealed a high inflammatory response (white blood cell count [WBC], 21,080/μL [neutrophil, 85.8%]; C-reactive protein [CRP] level, 19.5 mg/dL), and a bacterial infection was suspected." (PMID 33023518, 2020). "In earlier publications it has been shown that CRP is a powerful tool for ruling out patients with bacterial infections." (PMID 32144345, 2020). "The data presented here suggests that PCT and CRP both have only a moderate accuracy for detecting serious bacterial infections when use indiscriminately in febrile children attending the emergency department." (PMID 33087092, 2020). "Recently, CRP is widely used clinically to evaluate disease progression, and it served as an indicator for predicting bacterial infections in patients." (PMID 32867787, 2020). "Peripheral blood leucocytosis and high CRP are frequently used as biomarkers of bacterial infection in routine clinical practice in the ED." (PMID 32690014, 2020). "We also showed that compared to PCT, CRP is a more sensitive and specific marker for diagnosing bacterial infection in SLE33." (PMID 33199770, 2020). "Elevated lymphocytes, normal neutrophils with elevation or normal CRP levels can predict viral causes of URTI while the raise in neutrophils and CRP are more likely to predict bacterial infections." (PMID 33116166, 2020). "While bacterial infections have been reported in 55% (462/839) to 78% (35/42) of human patients with CRP concentrations > 100 mg/l, only 22% (33/149) of canine patients in our study fell into this category." (PMID 32434519, 2020). "As another frequently used biomarker for bacterial infection, we also evaluated the age‐related difference of serum CRP level." (PMID 32876981, 2020). "CRP is an acute-phase reactant protein synthesized by the liver in response to elevated cytokine levels and has been studied as a sensitive marker of bacterial infection." (PMID 32429293, 2020). "In human medicine, extremely high CRP (C-reactive protein) concentrations > 100 mg/l are indicators of bacterial infection and the need of antibiotic treatment." (PMID 32434519, 2020). "In two recent studies, CRP with extreme leukocytosis was proposed to be useful in predicting severe bacterial infection in children." (PMID 32429293, 2020). "Seventeen patients (9.3%) had a peak serum C-reactive protein (CRP) level > 100 mg/L (mimicking bacterial infection), with the highest being 193.09 mg/L." (PMID 33081701, 2020). "In light of the imperfection of both clinical features and laboratory parameters such as CRP, novel diagnostics measures are needed to better distinguish between viral and bacterial infections and thereby help reducing unwarranted antibiotic therapy." (PMID 32807104, 2020). "Elevated WBC count, neutrophil count, and CRP level are the common inflammatory indicators in bacterial infection." (PMID 32612961, 2020). "One study showed that the CRP level is more sensitive and specific in diagnosing bacterial infection than the PCT level." (PMID 33199770, 2020). "Procalcitonin (PCT) increases in response to pro-inflammatory stimuli, particularly of bacterial origin, where the sensitivity and specificity of which as a bacterial infection marker is claimed to be superior to CRP." (PMID 32498475, 2020).
bacterial infection (continued). "The aim of this study was to train and validate the IMS to differentiate between arboviral and common bacterial infections in Southeast Asia and compare its performance against C-reactive protein (CRP) and procalcitonin (PCT)." (PMID 30870415, 2019). "The median C-reactive protein (CRP) level of 48.8 mg/l in the blood were compatible with bacterial infections (upper limit of normal 5 mg/l), together with findings of SBP in 21% of the patients." (PMID 30800122, 2019). "To conclude, in the present study, both PCT and CRP have been demonstrated to have the capacity to differentiate potential bacterial infection from the flare of GPP itself." (PMID 31777354, 2019). "Areas under the receiver operating characteristic curves for invasive bacterial infection, diagnosed in 19 tested cases, were 94.3% for CRP and 91.7% for PCT." (PMID 31664120, 2019). "Our study showed that a normal level of CRP (<10 mg/L) made the diagnosis of invasive bacterial infection very unlikely." (PMID 31664120, 2019). "Overall, CRP with a cut-off of 40mg/L had a somewhat higher sensitivity for bacterial infections than the IMS with a somewhat lower specificity." (PMID 30870415, 2019). "In cases of acute inflammation and bacterial infection, CRP levels can be even higher, ranging from 40 to 200 mg/L." (PMID 31101112, 2019). "Considering the fact that C-reactive protein can be elevated in both viral and bacterial infections, it lacks specificity to differentiate bacterial form viral infections." (PMID 32440298, 2019). "Overall, the trained IMS performed comparable to CRP with the latter having a slightly higher sensitivity but lower specificity to diagnose bacterial infections." (PMID 30870415, 2019). "Previous data suggested that serum CRP levels were a better predictor of bacterial infection in febrile children compared to WBC, ANC or ABC counts." (PMID 31370781, 2019). "PCT and CRP performed equally well to differentiate bacterial infection from non-bacterial infection in GPP patients based on the areas under the ROC curves." (PMID 31777354, 2019). "While some investigators reported usefulness of PCT for diagnosing bacterial infection in the elderly, others revealed that PCT was inferior to CRP for predicting bacterial infection in these population." (PMID 30616612, 2019). "PCT has been found to be 7% more sensitive and 23% more specific than CRP for establishing the diagnosis of bacterial infection." (PMID 31691767, 2019). "CRP point-of-care tests (POCTs) had been designed to help healthcare staff at the primary-care level to distinguish bacterial from non-bacterial infections." (PMID 30736818, 2019). "Several studies showed superiority of procalcitonin as a diagnostic marker of bacterial infection relative to other biomarkers such as ESR and C-reactive protein." (PMID 32440298, 2019). "Laboratory findings such as neutrophil, lymphocyte and WBC counts, and acute phase reactants such as CRP are routinely used for the detection of bacterial infections." (PMID 31428594, 2019). "The aim of the present study was to compare the discriminative diagnostic properties of PCT and CRP for bacterial infection in GPP patients and to define appropriate cut-off values for the recognition of bacterial infection." (PMID 31777354, 2019). "For diagnosis of bacterial infection in CRP at a cut-off value of 12.15 mg/L, the sensitivity and specificity were 96.6% and 83.3%, respectively." (PMID 29623264, 2018). "Using receiver operating characteristic analysis, area under curve (AUC) to diagnose bacterial infection was 0.948 (95% confidence interval [CI]: 0–1.000) for CRP (P = 0.001) compared with 0.807 (95% CI: 0.668–0.947) for PCT (P = 0.019)." (PMID 29623264, 2018). "Laboratory tests should be run for inflammatory markers that can reveal severe bacterial infections associated with the perforation, such as white blood cell count (WBC) and C-reactive protein (CRP)." (PMID 29416554, 2018).
bacterial infection (continued). "The results are promising because CRP wassignificantly higher in bacterial infection compared with patients withoutinfection." (PMID 29846409, 2018). "The result suggested that the concentration of CRP inpatients with bacterial infection was much higher than that of control." (PMID 29846409, 2018). "C-reactive protein is a marker for inflammation, and its levels increase during bacterial infection." (PMID 29706967, 2018). "Procalcitonin (PCT), a promising marker to distinguish between bacterial and non-bacterial infection, shows lower sensitivity than CRP in patients with SI." (PMID 29356895, 2018). "It has been shown to differentiate bacterial infection from acute flare in rheumatoid arthritis, with superiority over conventional biomarkers such as CRP, ESR and WCC." (PMID 30225546, 2018). "Procalcitonin (PCT) alone, and also in combination with C-reactive protein (CRP) has been long recognized as a marker of the systemic inflammatory response to bacterial infections." (PMID 29596458, 2018). "CRP was highly sensitive and very specific for defining bacterial infections (AUROC curve 0.9059), when directly comparing bacterial and viral groups, consistent with data from previous fever studies from Southeast Asia." (PMID 29852003, 2018). "It is also reported that PCT is a more accurate marker for a differential diagnosis of bacterial infections compared to C-reactive protein (CRP)." (PMID 29675434, 2018). "The cut-off level detected for CRP in our study was 56.5 mg/L, which is comparatively low for the detecting of bacterial infections." (PMID 30344287, 2018). "In the elderly, serum CRP begins to rise 6 h after a bacterial infection with the peak reached after 48 h and a half-life of 19 h." (PMID 30193587, 2018). "In patients with SIRS the capacity of HNL to detect bacterial infection was compared to that of CRP and procalcitonin (PCT)." (PMID 29473432, 2018). "The use of PCT and CRP as biomarkers for discriminating bacterial infection has beendiscussed in various studies, but this is the first meta-analysis that involvedcomparing the difference of PCT and CRP in patients infected by differentpathogens." (PMID 29846409, 2018). "Both PCT and CRP levels inpatients with G− bacterial infection were higher than in those with G+ bacterialinfection and fungus infection." (PMID 29846409, 2018). "It plays a critical role, especially in the induction of CRP and fibrinogen synthesis in the liver during the course of bacterial infection." (PMID 29675434, 2018). "The concentration of CRP in patients infected by G− bacteria was much higher thanthat of G+ bacterial infection and fungus infection groups, and the G+ bacterialinfection also had higher concentrations than the fungus infection group." (PMID 29846409, 2018). "Previous studies have reported that PCT has a better sensitivity than CRP todifferentiate bacterial infections from non-bacterial infections, and thereliability of the application of CRP in guiding antibiotic therapy still hadproblems." (PMID 29846409, 2018). "The detection of inflammatory biomarkers such as IL-6 and C-reactive protein (CRP) in urine hold significance in the preliminary detection of chronic diseases as well as bacterial infections." (PMID 29796304, 2018). "Procalcitonin (PCT) and C-reactive protein (CRP) are already known predictive markers in serious bacterial infections, and it is emphasized that these biomarkers can be used as a marker of increased mortality in critically ill patients." (PMID 30675399, 2018). "The optimal cut-off value of CRP for bacterial infection diagnosis is 12.15 mg/L (96.6% sensitivity and 83.3% specificity), with an AUC of 0.948, which is similar to previous report." (PMID 29623264, 2018). "Conversely, as illustrated earlier, CRP is a sensitive marker for bacterial infection in SLE and has been shown to be superior to procalcitonin as a biomarker for this condition." (PMID 30225546, 2018).
bacterial infection (continued). "The highest concentrations of CRP are found in serum, with some bacterial infections increasing levels up to 1,000-fold." (PMID 29706967, 2018). "The PCT also increases the sensitivity of CRP and permits avoiding false positive results, as it is a more specific marker for bacterial infections, although the trauma and surgery show a transient increase." (PMID 29138696, 2017). "PCT in combination with CRP is valuable in the diagnosis of COPD in combination with bacterial infection and reasonable use of antibacterial drugs." (PMID 28811772, 2017). "The specificity and sensitivity of diagnosing COPD in combination with bacterial infection with PCT or CRP were lower than those of PCT in combination with CRP." (PMID 28811772, 2017). "PCT level in combination with CRP level is a sensitive and specific index for determining the existence of bacterial infection in AECOPD patients." (PMID 28811772, 2017). "FebriDx is a novel point-of-care test designed to identify systemic host immune responses to viral and bacterial infection through rapid measurement of MxA and CRP from a small sample of capillary blood." (PMID 28991170, 2017). "Acute phase reactants like C-reactive protein (CRP) have been used as indicators of bacterial infections since the 1970s." (PMID 27348760, 2017). "CRP has been shown to be a rapid useful predictor of bacterial infection and has guided clinicians (from developed countries) in reducing antimicrobial use." (PMID 28451028, 2017). "High serum CRP is correlated with sputum purulence and raised serum leucocyte counts and serum CRP is higher in the presence of bacterial infection." (PMID 28969667, 2017). "The serum level of CRP increases rapidly during infections, particularly in severe bacterial infections." (PMID 28969667, 2017). "CRP has been shown to be a rapid useful predictor of bacterial infection and has guided clinicians in reducing antimicrobial use." (PMID 28451028, 2017). "As CRP levels are especially raised in the presence of bacterial infection the treatment effect of antibiotics increase with higher values of CRP." (PMID 28969667, 2017). "Levels of CRP in combination with PCT is a reliable index for determining the existence of bacterial infection, which is of great clinical guidance significance to the treatment and prognosis assessment of AECOPD patients." (PMID 28811772, 2017). "The optimal cut-off value of CRP for diagnosis of bacterial infection was calculated to 37.3 mg/L, giving a specificity of 77.8% and sensitivity of 74.2% compared with gold standard." (PMID 28451028, 2017). "For example, as the strongest activator of the hepatic acute-phase response, IL-6 mediates the secretion of a group of proteins, including C-reactive protein, serum amyloid A, haptoglobin, and α1-acid glycoprotein during bacterial infections." (PMID 27579592, 2016). "The underlying logic is that there is no need to know the exact cause of AG for a successful treatment, particularly if there is indication of a bacterial infection, such as an elevated CRP level." (PMID 27603141, 2016). "The inflammation markers that showed statistically significant differences in bacterial versus non-bacterial infection patients were: CRP, PCT, calprotectin, soluble angiopoietin 2 receptor (sTie-2), and soluble triggering receptor on myeloid cells (sTREM-1)." (PMID 27486746, 2016). "CRP was used to differentiate between viral and bacterial infection on the presumption that an unspecified bacterial infection indicated the need for antibiotics (Quotation L)." (PMID 27188438, 2016). "In the largest study of these biomarkers in a tropical, Southeast Asian context, CRP was found to outperform procalcitonin in its ability to discriminate between viral and bacterial infections in well-characterised samples from febrile patients." (PMID 27027303, 2016).